PSMD14 (proteasome 26S subunit, non-ATPase 14)
Diseases named in the same sentence as PSMD14 in open-access papers (continued):
Sharing a sentence is not in itself a finding about the gene and the disease.
hepatocellular carcinoma (18 papers, 2015 to 2025). A malignant tumor that arises from hepatocytes. "PSMD14 also enhances hepatocellular carcinoma growth and metastasis by inhibiting GRB2 via deubiquitination and stabilizes LRPPRC via deubiquitination." (PMID 38643468, 2024). "The expression of PSMD14 is significantly higher in hepatocellular carcinoma than in normal liver tissues, and the knockdown of PSMD14 expression inhibited hepatocellular cancer proliferation and metastasis by down-regulation of GRB2." (PMID 36632137, 2023). "Among the prognostically characterized aging genes, EZH2, G6PD, LGALS3 and PSMD14 were significantly differentially expressed in hepatocellular carcinoma samples from the TCGA database." (PMID 37853322, 2023). "In contrast, PSMD14 is an independent prognostic factor in hepatocellular carcinoma and non-small cell lung cancer." (PMID 35750900, 2023). "PSMD14 has been recently reported to play important roles in other cancers, such as lung adenocarcinoma, hepatocellular carcinoma, glioma, and esophageal squamous cell carcinoma." (PMID 34383385, 2022). "Previous studies have demonstrated that PSMD14 is upregulated in cancers, such as prostate cancer and hepatocellular carcinoma." (PMID 34382324, 2021). "Mechanistically, PSMD14 has been observed to play oncogenic roles in head and neck squamous cell carcinoma, glioma, and hepatocellular carcinoma by inhibiting ubiquitination and degradation of cancer‐associated transcriptional factor E2F1." (PMID 34382324, 2021). "Decreased K48‐linked ubiquitination on GRB2 induced by PSMD14 increases the stability and protein level of GRB2, promoting hepatocellular carcinoma progression." (PMID 34382324, 2021). "Increased stability of GRB2 and TGF‐β receptors induced by PSMD14 overexpression can hyperactivate their signaling to enhance hepatocellular carcinoma growth and metastasis." (PMID 34382324, 2021). "Similarly, in hepatocellular carcinoma, PSMD14-mediated deubiquitination stabilizes CARM1, leading to the transcriptional activation of FERMT1 and subsequent promotion of proliferation and metastasis." (PMID 41488674, 2025). "Additionally, PSMD14 can accelerate hepatocellular carcinoma development and metastasis by stabilizing GRB2." (PMID 36959615, 2023). "PSMD14 enhances hepatocellular carcinoma growth and metastasis." (PMID 36424389, 2022). "PSMD14 is a kind of deubiquitinating enzymes (DUBs) and was reported to be connected with tumor progression and poor prognosis in many types of cancer including neck squamous cell carcinoma, non-small cell lung cancer, ovarian cancer, and hepatocellular carcinoma." (PMID 35898492, 2022). "Accruing evidence suggested that PSMD14, a member of JAMM family of DUB, exerts oncogenic functions in several human cancers, such as prostate cancer, hepatocellular carcinoma, lung adenocarcinoma, and colorectal cancer." (PMID 34382324, 2021).
ovarian carcinoma (14 papers, 2018 to 2025). A malignant neoplasm originating from the surface ovarian epithelium. "Taken together, these data suggest that upregulated PSMD14 is associated with ovarian cancer progression." (PMID 34382324, 2021). "Upregulated in ovarian cancer tissues, the level of PSMD14 expression was positively associated with FIGO stage and negatively associated with overall survival in ovarian cancer patients." (PMID 34382324, 2021). "A study of the molecular bases of aberrant autophagy in ovarian cancer which was found to be associated with an enhanced expression of the selective autophagy receptor SQSTM1/p62 has led to the identification of RPN11/PSMD14 as a negative regulator of autophagy levels." (PMID 39430244, 2024). "PSMD14 inhibits autophagy and thus influences the progression of ovarian cancer through the LRPPRC/Beclin1-Bcl-2/SQSTM1 signaling pathway." (PMID 40182048, 2025). "There were also reports that overexpression of PSMD14 promoted the progress of ovarian cancer and gastric cancer." (PMID 38327651, 2023). "On analyzing the relationship of PSMD family and ovarian cancer, the expression levels of PSMD8 and PSMD14 mRNA in ovarian cancer were found to be significantly higher than those in normal ovarian tissue." (PMID 37349676, 2023). "PSMD14 also promotes the progression of ovarian cancer by decreasing the enzymatic activity of PKM2." (PMID 36632137, 2023). "The mRNA expression levels of PSMD8 and PSMD14 in ovarian cancer tissues were significantly higher than those in normal ovarian tissues." (PMID 37349676, 2023). "PSMD14 is overexpressed in ovarian cancer tissues and is a biomarker and therapeutic candidate for ovarian cancer." (PMID 37485655, 2023). "PSMD14 promoted proliferation, invasion, and migration of ovarian cancer cells in vitro and ovarian tumor growth in vivo." (PMID 34382324, 2021). "To confirm the specificity of OPA against PSMD14 protein, we further treated PSMD14 stable knockdown ovarian cancer cells with OPA." (PMID 34382324, 2021). "More importantly, PSMD14 inhibitor OPA was uncovered as a potential drug in ovarian cancer treatment." (PMID 34382324, 2021). "Taken together, the antitumor effect of OPA in ovarian cancer cells is based on its inhibition of the ability of PSMD14 to decrease ubiquitination on PKM2." (PMID 34382324, 2021). "But we did not observe pronounced reduction in the growth, invasion, or migration of these cells, demonstrating that OPA impaired the malignant behavior of ovarian cancer cells by specifically targeting PSMD14." (PMID 34382324, 2021). "Collectively, PSMD14 plays oncogenic roles in ovarian cancer by stimulating proliferation, invasion, and migration, and its DUB activity is essential for its functions in ovarian cancer progression." (PMID 34382324, 2021). "We observed higher PSMD14 level in primary epithelial ovarian cancer and epithelial ovarian borderline tumor compared with that in normal ovarian tissues." (PMID 34382324, 2021). "Taken together, these data demonstrated an inhibitory effect of PSMD14 inhibitor OPA on ovarian cancer progression." (PMID 34382324, 2021). "To investigate the functions of PSMD14 in the malignant biological behaviors of ovarian cancer cells, we firstly examined the endogenous expression of PSMD14 in three ovarian cancer cell lines, including A2780, HO‐8910, and OVCAR‐3." (PMID 34382324, 2021). "In conclusion, the present study demonstrated that PSMD14 is overexpressed in ovarian cancer and promotes ovarian cancer progression by interacting with PKM2." (PMID 34382324, 2021). "Kaplan–Meier analyses revealed that high PSMD14 expression was related to poor overall survival and progression‐free survival in ovarian cancer patients." (PMID 34382324, 2021). "PSMD14 was highly expressed in 64% of primary epithelial ovarian cancer specimens, 50% of epithelial ovarian borderline tumor specimens, and none of the epithelial ovarian benign tumor or normal ovarian tissues." (PMID 34382324, 2021).
ovarian carcinoma (continued). "In the present study, we firstly reported the oncogenic roles for PSMD14 in ovarian cancer by detecting its clinical significance in ovarian cancer patients and exploring its influence on malignant behaviors of ovarian cancer in vitro and in vivo." (PMID 34382324, 2021). "PSMD14 inhibitor OPA effectively inhibits malignant biological behaviors of ovarian cancer in vitro and ovarian tumor growth in vivo." (PMID 34382324, 2021). "Our study disclosed PSMD14 as a novel DUB involved in metabolic reprogramming in ovarian cancer by interacting with PKM2." (PMID 34382324, 2021). "To verify these results, we further used GEPIA database and consistently observed higher expression level of PSMD14 in ovarian cancer tissues compared with that in normal ovarian tissues." (PMID 34382324, 2021). "Relationships between PSMD14 expression in epithelial ovarian cancer and clinicopathological parameters." (PMID 34382324, 2021). "Also, deubiquitination plays a significant role in ovarian carcinogenesis, for example, deubiquitinase PSMD14 is highly expressed in ovarian cancer and promotes ovarian cancer progression by reducing the ubiquitination of substrates." (PMID 39253578, 2024). "The available evidence supports that the contribution of RPN11/PSMD14 to ovarian cancer aggressiveness may derive from the cooperation among different mechanism, because it has been reported to decrease the enzymatic activity of pyruvate kinase M2 (PKM2)." (PMID 39430244, 2024). "Therefore, our results suggested that PSMD14 contributes to metabolic reprogramming by inhibiting PK activity and inducing Warburg effect in ovarian cancer cells." (PMID 34382324, 2021). "However, the function and mechanism of deubiquitinating enzyme 26S proteasome non‐ATPase regulatory subunit 14 (PSMD14) in the progression of ovarian cancer (OV), the deadliest gynecological cancer, still remains to be characterized." (PMID 34382324, 2021). "To further confirm the effects of PSMD14‐mediated deubiquitination on PKM2 protein in ovarian cancer, we investigated whether the expression level and stability of PKM2 is regulated by PSMD14." (PMID 34382324, 2021). "Subsequently, we established ovarian cancer cell lines stably overexpressing wild‐type PSMD14 or PSMD14 mutants H113Q or C120S to investigate whether PSMD14 exerted oncogenic functions in ovarian cancer via its DUB activity." (PMID 34382324, 2021). "Downregulation of PSMD14 also inhibited colony formation in ovarian cancer cells." (PMID 34382324, 2021). "To explore the expression of PSMD14 in ovarian cancer, we first investigated the expression of PSMD14 in 44 primary epithelial ovarian cancer specimens, 10 epithelial ovarian borderline tumor, 5 epithelial ovarian benign tumor, and 10 normal ovarian tissues via IHC assay." (PMID 34382324, 2021). "Here, we elucidated the oncogenic roles of PSMD14 in ovarian cancer for the first time." (PMID 34382324, 2021). "In line with this work, we observed that PSMD14 reduces only K63‐linked polyubiquitin chain on PKM2 in ovarian cancer cells, changing the forms of PKM2 oligomers without influencing the stability of PKM2 protein." (PMID 34382324, 2021). "Enriched proteasome genes, including PSME4 and PSMD14, was exhibited in doxorubicin-derived resistant ovarian cancer cell line, suggesting that this proteasome pathway may be involved in the development of resistance to doxorubicin." (PMID 30001383, 2018). "Our results indicated that PSMD14 could be a novel gene involved in ovarian cancer progression." (PMID 34382324, 2021). "However, the function and mechanism of PSMD14 in ovarian cancer still need to be investigated." (PMID 34382324, 2021). "PSMD14 expression was high in 42% of HNSCC, 66% of non-small cell lung cancer and 64% of ovarian cancer." (PMID 35750900, 2023).
ovarian carcinoma (continued). "To investigate the therapeutic effect of PSMD14 inhibition on ovarian cancer, we next treated A2780, OVCAR‐3, and HO‐8910 cells with a reported PSMD14 inhibiter named O‐phenanthroline (OPA)." (PMID 34382324, 2021). "Specifically, RPN11/PSMD14 acts by reducing the ubiquitination on the K63 of PKM2 increasing the expression of the dimeric form and also favouring its nuclear translocation leading to aerobic glycolysis in tumors, including ovarian cancer." (PMID 39430244, 2024). "Statistical analyses showed that upregulated PSMD14 expression was positively correlated with higher International Federation of Gynecology and Obstetrics (FIGO) stage, indicating that overexpressed PSMD14 contributes to ovarian cancer progression." (PMID 34382324, 2021). "According to the results of Transwell and scratch assays, the invasion and migration abilities of ovarian cancer cells elevated after upregulation of wild‐type PSMD14, but did not change significantly after overexpression of PSMD14 mutants." (PMID 34382324, 2021). "To explore whether PSMD14 promoted malignant behavior of ovarian cancer cells through PKM2, we used RNA interference to downregulate PKM2 expression in ovarian cancer cells." (PMID 34382324, 2021). "Overexpressed wild‐type PSMD14, but not PSMD14 mutants, was observed to induce promotion on cell viability and colony formation in ovarian cancer cells." (PMID 34382324, 2021). "Additionally, to investigate whether PSMD14 inhibitor OPA impairs the malignant biological behaviors of ovarian cancer cells by preventing the ability of PSMD14 to modulate PKM2, we then applied OPA in ovarian cancer cells after downregulation of PKM2 expression." (PMID 34382324, 2021).
lung adenocarcinoma (13 papers, 2020 to 2025). A carcinoma that arises from the lung and is characterized by the presence of malignant glandular epithelial cells. "The results reveal a notable association between increased PSMD14 expression and adverse prognosis, highlighting its potential to serve as a novel biomarker for lung adenocarcinoma." (PMID 40475775, 2025). "PSMD14 is strongly associated with poor prognosis in lung adenocarcinoma (LUAD), and PSMD14 knockdown significantly inhibits cell growth and affects lung cancer progression by modulating p21 stability, leading to G1-phase arrest and cellular senescence." (PMID 40182048, 2025). "By addressing these pivotal elements, this study aspires to provide significant insights into the potential of PSMD14 as a promising biomarker for diagnostic and therapeutic strategies in lung adenocarcinoma, ultimately advancing our understanding of tumor biology and the immune microenvironment." (PMID 40475775, 2025). "Subsequent investigations should prioritize the clinical implications of PSMD14 and its viability as a therapeutic target within the realm of immunotherapy, to provide enhanced treatment modalities for patients diagnosed with lung adenocarcinoma." (PMID 40475775, 2025). "In summary, the present study underscores the critical involvement of PSMD14 in lung adenocarcinoma, especially regarding its capacity to influence cellular proliferation, immune responses, and the tumor microenvironment." (PMID 40475775, 2025). "Highly expressed PSMD2 and SMD14 were greatly related to lymph node metastases and TNM phase of lung adenocarcinoma, while high expression of PSMD2, PSMD7, PSMD14 were linked to poor OS and/ or disease-free survival (DFS) among these patients." (PMID 37337223, 2023). "PSMD14 had been shown to play an oncogenic role in the context of ovarian, prostate, hepatocellular, lung adenocarcinoma, and colorectal cancers." (PMID 37349676, 2023). "In the case of proteasomal degradation, consistently high levels of PSMD14, which regulates the de-ubiquitination substrate, may lead to a worse prognosis of lung adenocarcinomas." (PMID 34839279, 2021). "We also determined the roles of PSMD14 in the regulation of lung adenocarcinoma (LUAD) cell growth." (PMID 32226511, 2020). "In lung adenocarcinoma (LUAD), PSMD14 is upregulated not only at the transcriptional level but also at the protein level." (PMID 41488674, 2025). "High PSMD14 expression predicted a poor overall survival (OS) and disease-free survival (DFS) in lung adenocarcinoma (LUAD) patients." (PMID 32226511, 2020). "PSMD14 was upregulated in tumor tissues compared to para-tumor normal bone tissues in various malignancies, including non-small cell lung cancer (NSCLC), liver cancer, and lung adenocarcinoma." (PMID 38053170, 2023).
multiple myeloma (13 papers, 2018 to 2025). "For example, the transcription factor RELA activated PSMD14, resulting in a positive PSMD14/NSD2‐RELA feedback loop that promoted the occurrence of myeloma." (PMID 40066751, 2025). "Another study reported that RELA promoted the progression of myeloma through transcriptional activation of PSMD14." (PMID 40066751, 2025). "And PSMD14 inhibition can induce multiple myeloma cell apoptosis and overcome bortezomib resistance." (PMID 38482057, 2024). "Mounting evidence suggests that PSMD14 was crucial in promoting disease progression and drug resistance in several tumors, including colorectal and multiple myeloma." (PMID 38053170, 2023). "As such, a PSMD14 inhibitor may be applicable not only to melanoma, but also to other cancers, including multiple myeloma." (PMID 33154524, 2020).
esophageal squamous cell carcinoma (10 papers, 2019 to 2025). Esophageal squamous cell carcinoma (ESCC) is a type of esophageal carcinoma (EC) that can affect any part of the esophagus, but is usually located in the upper or middle third. "PSMD14 is highly expressed in a variety of cancers and acts as an oncogene to promote tumor development and progression; it has been suggested that PSMD14 may be involved in esophageal squamous cell carcinoma (ESCC) tumorigenesis." (PMID 41035918, 2025). "For instance, PSMD14 is upregulated in esophageal squamous cell carcinoma (ESCC) tissues and can promote tumor cell migration and invasion through the PSMD14/SNAIL axis." (PMID 36959615, 2023). "The high expression of PSMD14 has been shown to exert protoneoplastic effects in many cancer cells, including liver cancer, CRC, and esophageal squamous cell carcinoma." (PMID 36632137, 2023). "Furthermore, USP26 108, PSMD14 121, OTUB1 117, and EIF3H 119 deubiquitinate and stabilize Snail, enhancing esophageal squamous cell carcinoma (ESCC) cell migration and tumor metastasis in vivo and in vitro." (PMID 41208892, 2025).
head and neck squamous cell carcinoma (9 papers, 2021 to 2025). A squamous cell carcinoma that arises from any of the following anatomic sites: lip and oral cavity, nasal cavity, paranasal sinuses, pharynx, larynx, and salivary glands. "PSMD14 overcame drug resistance in head and neck squamous cell carcinoma by inhibiting E2F1 ubiquitination and degradation, improving Akt pathway activation and SOX2 transcription." (PMID 37349676, 2023). "In head and neck squamous cell carcinoma, PSMD14 can influence tumor cell proliferation, drug resistance, and cell stemness by blocking E2F1 ubiquitination and degradation, boosting Akt pathway activation, and promoting SOX2 transcription." (PMID 38053170, 2023). "Likewise, the increased expression of PSMD14 in head and neck squamous cell carcinoma, glioma, and liver cancer indicates its potential as both a biomarker and a therapeutic target." (PMID 40475775, 2025). "Additionally, PSMD14 inhibitors exhibit antitumor activity and overcome chemoresistance in head and neck squamous cell carcinoma." (PMID 41488674, 2025). "Similarly, in head and neck squamous cell carcinoma (HNSCC), PSMD14 decreased E2F1 ubiquitination and degradation, which improved AKT pathway activation and SOX2 transcription, thereby facilitating HNSCC growth, chemoresistance, and stemness." (PMID 36959615, 2023).